FOXP3 (forkhead box P3)
Diseases named in the same sentence as FOXP3 in open-access papers (continued):
Sharing a sentence is not in itself a finding about the gene and the disease.
tumor (continued). "Furthermore, as shown in the dot plots, Treg from tumor spleens and tumors had significantly increased Foxp3 non-collaboration genes." (PMID 34084175, 2021). "Their tumor-permissive effect is achieved either by restraining the proliferation of tumor-specific effector cells or by limiting the secretion of IL-2 and IFN-γ owing to the expression of CTLA-4, glucocorticoid-induced tumor necrosis factor receptor (GITR), and Foxp3." (PMID 34831048, 2021). "Also, 12 days after treatment, FoxP3+ cells were detected, irrespective of the treatment group, only in the periphery of the tumours." (PMID 34229458, 2021). "Given recent reports that the balance between effector and suppressor immune subsets may offer more useful prognostic information, we evaluated the correlation between ratios of CD8+/FOXP3+, CD3+/FOXP3+, CD4+/FOXP3+, and CD68+/CD163+ and survival in tumor samples at diagnosis and after NACT." (PMID 32852603, 2021). "We hypothesized that Foxp3 plays significant roles in promoting DEGs in Treg from normal tissues, non-tumor diseased tissues and tumor tissues." (PMID 34084175, 2021). "In summary (graphical abstract), we reveal that SPTBN1 functions as a tumor suppressor to stabilize SOCS1 protein, controlling the cellular level of p65 to suppress the expression of inflammatory cytokines, IL-1α, IL-1β and IL-6, and the expansion of MDSCs and Foxp3+Treg cells." (PMID 33754058, 2021). "Consequently, the high density of CD4+Foxp3+ T-cells in the tumor immune microenvironment could represent a state of immune activation, which may be the reason for the correlation between the density of CD4+Foxp3+ T-cells and OS in this study." (PMID 34647108, 2021). "Moreover, considering the elevation of FOXP3, IL-6, and IL-17 levels in these cells, exosomes secreted by CML cells may induce the fates of T cells toward tumor favorable T cells instead of conventional activated T cells." (PMID 34493241, 2021). "Additionally, a high density of forkhead box P3 (FOXP3) positive cells within the tumor does not appear to be a negative prognostic indicator." (PMID 33915839, 2021). "Moreover, the IL-21-producing T cells in the tumor tissues were FOXP3 negative, and the majority of these cells (84.5 ± 3.3%) were CD3 and CD4 positive." (PMID 34026621, 2021). "Consistently, Foxp3+ cells have been shown to surround CD163+ M2 macrophages, indicating that M2 macrophages stimulated by RANKL/RANK signaling might recruit effector Tregs into the tumor microenvironment of EMPD." (PMID 34436026, 2021). "However, in node-negative NSCLC, they determined that FoxP3+ tumor-infiltrating Tregs was an independent predictor of shorter recurrence-free survival." (PMID 34141625, 2021). "The immune response against the tumor could differ depending on sex, so that tumor-infiltrating CD8+ cytotoxic lymphocytes and FoxP3+ regulatory T lymphocytes prior to RCT in the biopsy and about 55 days after RCT in the surgical specimen were compared between sexes." (PMID 35008311, 2021). "Interestingly, YAP1 KO CD4 and CD8+ T cells demonstrated superior tumor infiltration compared to wild-type counterparts, and tumor growth was either greatly delayed or nearly absent in tumor-bearing CD4–Cre or Foxp3–Cre mice." (PMID 34685695, 2021). "Considering that flow cytometry of distant tumour-free liver samples demonstrated similar linear relationships between CD4+ T cells, CD4+FoxP3− T helper cells, the CD8/CD4 ratio, and the percentage of dHGP scored at the tumour–liver interface, HGPs could, at least in part, be host-determined." (PMID 32418992, 2020). "Our results indicate that FoxP3+ T-cells may exert site-specific anti-tumor effects but may not play an immunosuppressive role in OSCC." (PMID 32785290, 2020).
tumor (continued). "The underlying mechanism could be that plasmacytoid DCs (pDCs) in the PTC microenvironment induces the transformation of initial CD4+T cells into FoxP3+ICOS+Tregs through the inducible costimulatory ligand (ICOSL)-ICOS pathway hence resulting in Tregs enrichment and tumor escape." (PMID 32626535, 2020). "In the tumor ROI, we focused on stromal and epithelial tumor compartments and assessed their infiltration by monocytic CD11b+CD14+, granulocytic CD11b+CD15+, and immunosuppressive ARG1+ myeloid cells and also CD8+Ki67+/– cytotoxic and FOXP3+ regulatory T cells." (PMID 33193316, 2020). "Indeed, treatment induced a specific decrease in the number of activated Tregs (CD4+/Foxp3+/CTLA4+) in the tumor microenvironment, without modulating Ki67 and HLA-DR activation markers." (PMID 32681091, 2020). "Interestingly, CD4+FOXP3+ T cells had a close interaction with CD8+ T cells rather than tumor cells." (PMID 32377339, 2020). "Finally, the pDC/mDC ratio correlates with FoxP3+ Tregs recruitment in metastatic TDLNs of CRC patients, further supporting that pDCs might contribute to Tregs development in the tumor milieu." (PMID 32054102, 2020). "However, as these markers are not exclusive to Treg, detection of FOXP3 in tumor tissue is inferred to represent CD4+CD25+FOXP3+ Treg." (PMID 33013886, 2020). "A recent study has indicated that the percentages of CD4+CD25+FOXP3+Treg cells and CD4+IL-17+Th17 cells were significantly higher in HCC patients than in the healthy individuals; Moreover, the increased percentages of Treg and Th17 cells were closely related to the tumor stage and tumor size of HCC." (PMID 32847505, 2020). "Finally, we performed correlation analysis and discovered that the IF is multifaceted and may bear pro- and anti-tumor functions simultaneously, e.g., with higher expressions of CD8+ and FoxP3+ cells." (PMID 33192595, 2020). "Our results provide evidence that patients with increased CD4+FOXP3+ T cells and CD8+ T cells will not only have a favorable prognosis but may also be candidates for ICB as a result of high IFN‐γ and PDL1 expression in the tumor." (PMID 32377339, 2020). "However, there is no data on expression of VDR in context of quantity of FOXP3 expressing cells in CHL tumor microenvironment." (PMID 32513132, 2020). "While tumor infiltrating CD8+ T cells have been shown to be associated with positive outcomes and FOXP3+ Treg are usually associated with negative outcomes, there is tremendous heterogeneity in the results of IHC-based detection and enumeration of TIL subsets in cancer." (PMID 33013886, 2020). "Anti-CTLA-4 immunotherapy does not deplete Foxp3+ cells in human tumours, which suggests that their efficacy could be enhanced by modifying the Fc portions of the mAbs to enhance Fc-mediated depletion of intratumoral Tregs." (PMID 32680511, 2020). "Therefore, CD4, CD8, Foxp3, GrB, IL10, and CD68 immune cell markers were studied in order to explore if differences around EBV-infected CG cells and EBV+ tumor cells derived from GC cells could be involved in the malignant transformation." (PMID 31963774, 2020). "Indeed, AIRE, AchR and Foxp3 (the transcription factor that induces T-reg phenotype) mRNA levels are lower in tumor tissue from Tm patients without MG compared to those who have developed MG." (PMID 33260538, 2020). "Importantly, HBV infection was associated with higher levels of CCL22 and Foxp3 than no HBV infection, indicating more Tregs (Foxp3 positive) were recruited into the tumor tissues of HBV carriers than noncarriers." (PMID 31769216, 2020). "Tumor growth is suppressed in a xenograft Nur77/Nurr1-double knockout mouse model and the expression of Treg-signature genes, including Foxp3 and CTLA-4, is attenuated, without development of autoimmunity, but Nur77- or Nurr1-single knockout mice are not able to delay or inhibit tumor growth." (PMID 33086676, 2020).
tumor (continued). "The injection of VV-GM alone did not significantly affect Treg cells (CD4+FoxP3+) in tumor infiltrates, but the injection of VV-iPDL1/GM reduced Treg cells to a level lower than that in PBS-treated tumors, resulting in a robustly enhanced CD8+ T cells/Treg ratio." (PMID 32170083, 2020). "Foxp3 regulatory T cells were not increased inside the tumours." (PMID 32165639, 2020). "miR‐17 and especially miR‐19b appeared to strongly correlate with the proportion of CD3+ cells in the tumor infiltrate, while miR‐195 consistently showed positive associations with both proportion and density of CD3+, CD4+, CD5+, CD8+ and FOXP3+ cells, but not CD20+ cells." (PMID 33024560, 2020). "Then, analysis of different subpopulations of tumor infiltrating lymphocytes (TILs) by using biomarkers such as CD3 (pan T‐cell), CD8 (cytotoxic T‐cell), FoxP3 (regulatory T‐cell), and CD45RO (memory T‐cell) may help to identify predictive T‐cell signatures for immunotherapy." (PMID 31922656, 2020). "Analysis of the lymphoid immune cell subtypes in MyC-CaP demonstrated an increased tumour infiltrate of CD45+CD4+CD25+FoxP3+ Treg cells, and a non-significant reduction in the proportion of CD45+CD3+CD8+ T-cells, in 3 × 5 Gy RT-treated tumours versus untreated controls." (PMID 32641865, 2020). "Functionally, subsequent experiments demonstrated that compound 5d could effectively inhibit tumour cell proliferation, induce apoptosis, up-regulate the expression of IFN-γ and granzyme B, and suppress FoxP3+ Treg cell differentiation, thereby activate the immune system." (PMID 32466694, 2020). "In some dogs with adenocarcinomas, tumor recurrence might not be influenced by Foxp3+ Tregs, VEGFR2 or HIF‐1α, and may effectively take advantage of other critical microenvironmental factors." (PMID 32267594, 2020). "We showed that the heterogeneous tumor human leukocyte antigen-1 expressions differently affect the magnitude of cytotoxic T-cell infiltration and the distributions of CD20+ B cells and CD4+FOXP3+ regulatory T cells within and outside of T-cell infiltrated tumor areas." (PMID 31166985, 2019). "To understand the tumor microenvironment of AIPpos tumors, we evaluated expression of several key components of the tumor microenvironment using specific molecular markers for macrophages (CD68), T-reg cells (FOXP3), cytotoxic T cells (CD8), and memory T cells (CD45RO)." (PMID 30867568, 2019). "Moreover, the concomitant reduction in St2−/− mice of tumor load and CD4+ FOXP3+ Tregs and the findings that Treg-restricted St2 ablation is associated with reduced CRC development led us to hypothesize that ST2+ CD4+ FOXP3+ Tregs support CRC development." (PMID 31165767, 2019). "In contrast, the tumor elicited strong, tumor-specific Foxp3-negative Tfh-like responses in dLN." (PMID 31801070, 2019). "We found an association between the IFNγ T-cell response upon stimulation with tumor-specific HPV16 E6 peptides and PD-1 blockade, and lower levels of aTregs as well as elevated levels of a particular subset of CD8+ T cells, specifically CD8+FoxP3+CD25+ T cells." (PMID 30755279, 2019). "Notably, there was no increase in CD4+CD25+FoxP3+ T cells in all studied tissues in tumor-bearing (TBM) mice on SM16 diet." (PMID 31288845, 2019). "Moreover, (R)-crizotinib alone or with CDDP induced PD-1 expression on tumor-infiltrating CD4+ Foxp3− but not in CD4+Foxp3+ (Treg) cells bearing the exhaustion marker ICOS." (PMID 30940805, 2019). "In addition, anti-4-1BB treatment did not affect the Foxp3+ Treg conversion from Foxp3−CD4+ T cells in tumor-bearing mice regardless of CD73 expression." (PMID 30635578, 2019). "In addition, the frequency of CD4+ FOXP3+ Tregs, the proportion of ST2+ CD4+ FOXP3+ Tregs, and IL-33 protein expression in the colon all positively correlated with tumor scores (i.e. the sum of the relative size of all tumors in a given mouse), irrespective of the genetic background." (PMID 31165767, 2019).
tumor (continued). "Thus, targeting Tregs in tumor bearing hosts represents a strategy for tumor immunotherapy although studies in some human tumor tissues have suggested FOXP3 effects only as a contributory, but not a deterministic role, on tumor malignant growth." (PMID 30800128, 2019). "Interestingly, CXCL5, a chemokine known for its role in promoting the recruitment of MDSCs and TAMs towards tumor sites and its receptor CXCR2 in addition to the Tregs transcription factor FOXP3 were among the highly differentially expressed between the XRT group and XRT + GLZ group." (PMID 31015520, 2019). "PARP inhibition promotes differentiation of naïve T cells to Foxp3+ regulatory T cells, which suppress immune responses, and upregulates in tumor cells the expression of PD-L1, which by engaging PD1 dampens anti-tumor T cell responses favoring tumor immune-evasion." (PMID 31877876, 2019). "However, the FoxP3 negative conventional helper CD4 T cells (Tconv)/Treg ratios within the tumor were significantly elevated upon oncolytic VSV‐GP therapy compared to the PBS control group." (PMID 30972741, 2019). "The tumor microenvironment is rich in molecules and several possible mechanisms may increase the number of FOXP3+ Tregs, such as driving CD4+ T-helper cells to develop into FOXP3+ Tregs, recruiting existing FOXP3+ Tregs to tumor sites, and inducing the expansion of retained Tregs." (PMID 31852159, 2019). "Here, we demonstrate that CD4+ T cells when incubated with tumor-derived exosomes from mutant (MT) KRAS non-small-cell lung cancer (NSCLC) cells, patient sera, or a mouse xenograft model, induce phenotypic conversion to FOXP3+ Treg-like cells that are immune-suppressive." (PMID 31635338, 2019). "However, the increased rate of FoxP3 and Tbet co-expression by CD8+ T cells after NACT observed in the current study may be indicative of a positive role in anti-tumor immune responses." (PMID 31616965, 2019). "However, targeting α-SMA might increase the immunosuppressive CD3+Foxp3+ Tregs infiltrate in the TME, which ultimately led to aggressive tumor development." (PMID 31462327, 2019). "Compared with non-responders, responders show a trend to employ lower peripheral CD4+, CD8+, CD25+Foxp3+Treg and Gr-1+CD11b+MDSC cell density, higher CD8+ to Treg ratio, and similar PD-1+ fraction at day 10, which is consistent with the trend within tumour tissue except CD8+ cells." (PMID 30587849, 2019). "High CCL20 expression and increased FOXP3+ TILs infiltrates were both associated with high histological grade, axillary lymph node metastases, positive HER2, and high Ki67 index but not correlated with age, tumor size, ER status." (PMID 31852159, 2019). "However, neither Lgr5 expression nor intratumor FoxP3+ Tregs correlated with any clinicopathological characteristics, including tumor size, degree of differentiation and TNM classification." (PMID 31417548, 2019). "In our study, we found the compartmental localization of CD8+ and Foxp3+ cells might influence the impact of tumor immunity and only CD8+ cells in tumor area and Treg+ cells in surrounding stroma had relevance with clinical factors and tumor progression." (PMID 30474571, 2018). "Total cell counts across whole tumor sections were performed to determine immune-to-tumor cell ratio; CD8+, CD4+, and CD20+ lymphocytes increased 10-fold, 3-fold, and 2-fold, respectively, in the SC mts with respect to the primary tumor, while Foxp3+ cells were scarce." (PMID 29774030, 2018). "Importantly, the tumor microenvironment of surgical specimens from CAR T-Cell treated tumors in this trial displayed marked upregulation of PD-L1, IDO, and TGF-β, as well as FoxP3+ Tregs." (PMID 30568917, 2018). "Some CD8+ T, invariant NKT, B, epithelial and tumor cells could potentially express Foxp3, although not necessarily presenting suppressive activity." (PMID 30410119, 2018).
tumor (continued). "As the adaptive immune response to cancer is characterized by progressive development of TILs with a role to reduce the anti-tumour action of CD8+ cells, we were interested whether increase in FoxP3+ T-cells, the major counter-actors of CD8+ T-cells, will follow the increase in CD8+ TILs." (PMID 29394917, 2018). "In particular, the presence of lymphocyte markers including CD20, FoxP3, and T cell intracellular antigen-1 (TIA-1) are indicators of positive prognosis for patients manifesting HGSC, indicating recruitment of distinct populations of T cells to the tumor site to generate cytotoxic effects." (PMID 28929459, 2018). "Since tumour-infiltrating lymphocytes are the main effectors of immune-cell mediated death, immunohistochemistry was performed for the CD8+ T cell subset, granzyme B, a serine protease and marker of cytotoxicity of lymphocytes, and FoxP3, a putative marker of Tregs." (PMID 30327563, 2018). "Methylation levels at the FOXP3 locus was increased in LN CD4+ T cells from patient with muscle invasive pT2 compared to both non-muscle invasive pTa-Tis staged patients and to the cells from patients with perivesical infiltrating tumours (pT3) (p < 0.05 for both)." (PMID 30075815, 2018). "Moreover, a negative association was found between FOXP3 and VEGF expression in primary tumor samples (P < 0.001, R2 = −0.368)." (PMID 29970908, 2018). "In addition, outside the haemopoietic system, both FoxP3 and GATA-3 have various roles in tumour development which may be pro- or anti-tumorigenic, depending on the tumour type." (PMID 30559928, 2018). "However, tumor PD-L1-positive status (HR = 0.799, 95% CI: 0.602–1.061, P = 0.122) and high FOXP3+ T cell infiltration in tumor (HR = 1.188, 95% CI: 0.906–1.560, P = 0.213) were not independent predictors for AGC prognosis." (PMID 30003113, 2018). "Interestingly, transient increase in the levels of Il12b and Il12rb2 in splenocytes from mice treated with calcitriol and its analogs can contribute to the lack of effect on the Foxp3 expression level during the later stage of tumor progression." (PMID 30037009, 2018). "In addition, the percentage, IFN-γ production, BACH2 SUMOylation or suppressive function of tumor-infiltrating Treg cells from Foxp3-CreSenp3f/f mice treated with or without NAC displayed no apparent difference." (PMID 30089837, 2018). "We also found that patients with advanced-stage tumors had less CD4 and CD8, lower CD4/FOPX3 and CD8/FOXP3 ratios, and higher CD3/CD4 and CD3/CD8 ratios, which may suggest that as their tumors progressed, the tumor microenvironment shifted toward a more immunosuppressive environment." (PMID 30153850, 2018). "However, the tumor nest compartment for pattern I tumors showed significantly higher percent of FOXP3-positive cells (P = 0.002; data not shown)." (PMID 29874226, 2018). "Depending on the disease stage, the presence of CD8+ and absence of Foxp3+ T cell populations in tumor tissues correlated with improved GBC patient survival, and thus represent potential markers for prognosis and management of advanced disease, and supports testing of immunotherapy." (PMID 29499656, 2018). "Interestingly, when CD8+ T cells were co-cultured with normal kidney epithelial (NKE) cells, no CD8+CD25+FOXP3+ population were induced indicating that the induced CD8+ Treg cells are tumor specific and just any anonymous response to different cell lineages." (PMID 28487507, 2017). "Furthermore, FOXP3 could potently suppress the proliferation and invasion of HCC cells in vitro and reduce tumor growth in vivo." (PMID 28903735, 2017). "Therefore, we examined if some of the increased CD4+ T‐cells among the TME and tumor‐free bone of mice with subcutaneous tumors might be CD4+, CD25+, FoxP3+ T‐regs." (PMID 28250928, 2017).